TXN2 (thioredoxin 2)
Description:
Important for the control of mitochondrial reactive oxygen species homeostasis, apoptosis regulation and cell viability Is involved in various redox reactions including the reduction of protein disulfide bonds, through the reversible oxidation of its active center dithiol to a disulfide (By similarity).
Synonyms: MTRX; Mt-Trx; TRX2; COXPD29; TXN
Tractability: PROTAC: ubiquitination databases record sites on it; its protein half-life has been measured; a small molecule that binds it is known.
Target class: Enzyme; Oxidoreductase
Gene: Protein-coding gene on chromosome 22 (36,466,895 to 36,482,072, reverse strand). Ensembl gene ENSG00000100348.
Subcellular location: Mitochondrion
Subcellular location (Human Protein Atlas): Mitochondria
Pathways (Reactome):
Cellular responses to stimuli: Detoxification of Reactive Oxygen Species
Metabolism: Degradation of cysteine and homocysteine
Gene Ontology:
Molecular function: oxidoreductase activity, acting on a sulfur group of donors, disulfide as acceptor; protein binding; protein-disulfide reductase activity
Biological process: sulfur amino acid catabolic process
Cellular component: mitochondrion; mitochondrial matrix
Genetic constraint (gnomAD): Loss-of-function variants: 12 observed, 14.3 expected, observed/expected ratio (o/e) 0.84, 90% interval 0.54 to 1.36. The upper end of that interval is the gene's LOEUF score, 1.36, which puts it in group 5 of 6, group 1 being the genes least tolerant of losing a copy. Missense variants: 173 observed, 219.71 expected, observed/expected ratio (o/e) 0.79, 90% interval 0.69 to 0.89. Synonymous variants: 89 observed, 85.95 expected, observed/expected ratio (o/e) 1.04, 90% interval 0.87 to 1.24.
Homologues: Orthologues: chimpanzee TXN2 (100% identical), macaque TXN2 (98% identical), mouse Txn2 (89% identical), guinea pig TXN2 (88% identical), rabbit TXN2 (83% identical), pig TXN2 (78% identical), rat Txn2 (67% identical), tropical clawed frog txn2 (66% identical), zebrafish txn2 (54% identical), Caenorhabditis elegans trx-2 (34% identical), Drosophila melanogaster CG8517 (33% identical), Drosophila melanogaster CG8993 (31% identical). Paralogues in human: TXN (22% identical), TXNDC2 (22% identical), TXNL1 (20% identical), TXNDC8 (18% identical).
Diseases named in the same sentence as TXN2 in open-access papers:
TXN2 is named in the same sentence as 37 diseases in open-access papers, as found by Europe PMC text mining. Sharing a sentence is not in itself a finding about the gene and the disease. The quoted sentences say what the papers report.
lung carcinoma (4 papers, 2013 to 2025). "Studies conducted in regions with a high prevalence of lung cancer have linked bituminous coal pollution to specific genetic alterations, such as haptoglobin depletion and thioredoxin 2 (TXN2) overexpression, which contribute to increased treatment resistance by modifying ferroptotic pathways." (PMID 40066170, 2025). "All these results suggested that TXN2 overexpression and HP depletion promoted lung cancer resistance were through attenuating ferroptosis." (PMID 33528895, 2021). "In vitro, both knocking down of TXN2 and overexpression of HP were observed to modulate sensitivity of lung cancer cell lines to erastin and RSL." (PMID 33528895, 2021). "We validated the changes of TXN2 and HP in proteomics using several lung cancer cell lines and clinic samples." (PMID 33528895, 2021). "It was revealed that TXN2 up‐regulated and HP downregulated in lung cancer cell tissues of Xuanwei patients and 3 lung cancer cell lines." (PMID 33528895, 2021). "Specifically, in the present study, we supposed that HP and TXN2 may be involved in ferroptosis and contribute to lung cancer in Xuanwei area." (PMID 33528895, 2021). "Together, our results demonstrate that down‐regulated TXN2 and up‐regulated HP made the cancer cells more resistant, which could be a specific mechanism for the lung cancer in Xuanwei area." (PMID 33528895, 2021). "We overexpressed TXN2 or interfered with HP in lung cancer cell lines (A549 and NCI‐H11299)." (PMID 33528895, 2021). "We hypothesized ‐ that regulating the levels of TXN2 and HP in lung cancer cells would influence the cell proneness to ferroptosis." (PMID 33528895, 2021). "TXN2 overexpression or HP depletion decreased erastin and RSL‐induced lipid oxidation in lung cancer cell lines, which were shown by the green fluorescence intensity (levels of oxidized C11 BODIPY 581/591)." (PMID 33528895, 2021). "All three lung cancer cell lines (A549, H2009, SBC-1) showed detectable levels of PGE2, PGD2, PGF2α, TXN2 and 6ketoPGF1." (PMID 23637858, 2013). "Further experiments on the two differential proteins, thioredoxin 2 (TXN2) and haptoglobin (HP), showed that the change of their expressions could make the lung cancer cell lines more resistant to erastin or RSL‐induced ferroptosis in vitro, and promote the growth of tumour in nude mice." (PMID 33528895, 2021).
epilepsy (3 papers, 2020 to 2025). A brain disorder characterized by episodes of abnormally increased neuronal discharge resulting in transient episodes of sensory or motor neurological dysfunction, or psychic dysfunction. "Txn2 deficiency impairs mitochondrial redox homeostasis and causes early-onset neurodegeneration with severe cerebellar atrophy, epilepsy, dystonia, optic atrophy, and peripheral neuropathy." (PMID 40533307, 2025). "Recessive variants in TXN2 have demonstrated microcephaly, cerebral atrophy, psychomotor delay, epilepsy, optic atrophy, and retinopathy." (PMID 33426505, 2020).
lung adenocarcinoma (2 papers, 2020 to 2021). A carcinoma that arises from the lung and is characterized by the presence of malignant glandular epithelial cells. "The present study was designed to evaluate the association between antioxidant gene polymorphisms (SOD rs5746136 and SOD rs4880; CAT rs769218; OGG1 rs1052133; and TXN2 rs4821494) and EGFR-mutated lung adenocarcinoma." (PMID 32937815, 2020).
rheumatoid arthritis (2 papers, 2019 to 2023). A chronic, systemic autoimmune disorder characterized by inflammation in the synovial membranes and articular surfaces. "We chose to evaluate auranofin, as it is an FDA-approved drug for rheumatoid arthritis and is known to downregulate Txn2." (PMID 37298855, 2023).
adenovirus infection (1 paper, 2021). "miR-27 can affect adenovirus infection by targeting the 3′UTR region of SNAP25 and TXN2." (PMID 34360898, 2021).
endometriosis (1 paper, 2020). The growth of functional endometrial tissue in anatomic sites outside the uterine body. "The SNP in TXN2 (rs4821494) also showed a difference in allele frequency (G:T = 180 (69.2%):80 (30.8%) in control and G:T = 141 (78.3%):39 (21.6%) in endometriosis group, p = 0.030)." (PMID 32679649, 2020). "Further research with a larger sample size and preferably immunnohistological stains for GPX4 and TXN2 expression is warranted to understand their roles in development of endometriosis." (PMID 32679649, 2020). "In the codominant model, the GG, GT and TT genotype frequencies of TXN2 (rs4821494) were 54 (60%), 33 (36.7%) and 3 (3.3%) in endometriosis group and 60 (46.2%), 60 (42.2%) and 10 (7.7%) in the control group." (PMID 32679649, 2020). "In this study, we compared the genetic variation of three antioxidant enzymes, GPX4, TXN2 and TXNRD1 and attempted to identify whether there is any difference in allele frequency between endometriosis and control patients." (PMID 32679649, 2020). "In an attempt to answer this question, this study compared the genetic variants of three different oxidative stress enzymes (GPX4, TXN2 and TXNRD1) and evaluated if there is a difference in genotype and allele frequency between women with endometriosis and healthy controls." (PMID 32679649, 2020). "In conclusion, the relationship between endometriosis and SNP of antioxidant enzymes, GPX4 and TXN2, was confirmed by the present study." (PMID 32679649, 2020). "This prospective case-control study attempted to check the connection between single nucleotide polymorphism (SNP) of three antioxidant enzymes (glutathione peroxidase 4 (GPX4), thioredoxin 2 (TXN2), thioredoxin reductase 1 (TXNRD1)) and endometriosis." (PMID 32679649, 2020). "This study focused on a SNP of the TXN2 gene (rs4821494) and a SNP of the TXNRD1 (rs1128446), both have been reported to be overexpressed by cancer cells, but currently no strong evidence in relation to endometriosis." (PMID 32679649, 2020).
Hypertension (1 paper, 2014). The presence of chronic increased pressure in the systemic arterial system. "Altered function of this system has been implicated in hypertension and although resveratrol can activate thioredoxin-2 which confers benefit in heart disease, it is unclear whether this also has beneficial impact in hypertension." (PMID 25140155, 2014).
liver disease (1 paper, 2023). "When the liver is impaired in alcohol metabolism, gene expression in the liver (such as Txnrd1, Txnrd3, Txn1, and Txn2) decreases significantly, indicating the risk of liver disease and the need for timely intervention." (PMID 36765968, 2023).
melanoma (1 paper, 2019). A malignant, usually aggressive tumor composed of atypical, neoplastic melanocytes. "Similarly, the up-regulated genes in the ABCB5 CTC fractions were involved in metastasis (CALU, CYB5R1, DUSP3, CREG1, ENDOD1), tumour growth, and/or melanoma biology (H1F0, SCNA, WIPI1, TXN2)." (PMID 30769764, 2019).
mesothelioma (1 paper, 2023). A usually malignant and aggressive neoplasm of the mesothelium which is often associated with exposure to asbestos. "In addition, they demonstrated that thiostrepton and gentian violet, which downregulate TXN2, were associated with decreased tumor growth in mice mesothelioma xenografts." (PMID 37298855, 2023).
tumor (8 papers, 2012 to 2023). "Overexpression of mitochondrial Thioredoxin-2 (Trx2) improves EC proliferation and arteriogenesis in the ischemic limb and cancer researchers now utilize mitochondrial uncouplers in attempts to reduce tumor size due to their effects on neovascularization." (PMID 26635622, 2015).
cancer (5 papers, 2015 to 2025). A tumor composed of atypical neoplastic, often pleomorphic cells that invade other tissues. "Furthermore, NFKB1 and HIF1 expression were negatively correlated with CDK5 and TXN2 in all three cancers, while HIF1-NFKB1 showed a positive association with each other." (PMID 32033319, 2020). "Out of 9 classifiers based on mtFE scores, 4 proteins (i.e. Lonp1, Sod1, Txn2 and Ogdh) were identified as potential cancer drivers in a forward genetic screen in mice, in comparison with 1 and 3 in mito and lysate data, respectively." (PMID 31061415, 2019). "For instance, Lonp1 and Txn2 are frequently induced by various stimuli in the cell, including hypoxia and the production of reactive oxygen species (ROS), and can therefore regulate cancer cell apoptotic resistance." (PMID 31061415, 2019). "The thioredoxin-2 (TXN2) system also plays a crucial role in redox regulation and resistance to apoptosis, further supporting cancer progression." (PMID 40110186, 2025).
infection (2 papers, 2017 to 2020). The state of being infected such as from the introduction of a foreign agent such as serum, vaccine, antigenic substance or organism. "The level of BmTPx-Q expression reached a peak, whereas B. microti parasitemia decreased to low levels at 8 days post-infection, similar results were also observed for B. microti other antioxidant enzymes, such as peroxiredoxin 2, thioredoxin 2, and thioredoxin 3 in previous studies." (PMID 32133382, 2020).
TXN2 also shares sentences with these, for which no sentence is quoted: optic atrophy (3 papers); Cerebellar atrophy (2); Dystonia (2); glaucoma (2); peripheral neuropathy (2); Cerebral atrophy (1); diabetic neuropathy (1); Duchenne muscular dystrophy (1); Friedreich ataxia (1); fungal infections (1); glioblastoma (1); glioma (1); hereditary optic neuropathy (1); Hyperglycemia (1); Insulin resistance (1); lung squamous cell carcinoma (1); microcephaly (1); multiple sclerosis (1); neurological diseases (1); pancreatic cancer (1); psychomotor delay (1); retinoblastoma (1); retinopathy (1); steatosis (1).